NRP1 (neuropilin 1)
Diseases named in the same sentence as NRP1 in open-access papers (continued):
Sharing a sentence is not in itself a finding about the gene and the disease.
tumor (continued). "At the endpoint of 7 weeks, mean tumor diameter of NT-BTSCs (13.1 mm ± 2.4) was greater than that of Nrp1-KD BTSCs (0.0 mm ± 0.0), and approached significance for PlxnA1-KD BTSCs (5.6 mm ± 1.4)." (PMID 33302912, 2020). "This contrasts with several studies in which NRP-1 blockade showed differences in tumor growth already in the early stages of tumor development." (PMID 33266104, 2020). "As a co-receptor of VEGFR, NRP1 also plays a key role in angiogenesis, development, tumour growth and metastasis." (PMID 32303680, 2020). "In vivo study also shows that gene deletion of NRP1 in tumor infiltrating macrophages exerts an anti-cancer function through suppression of an immune suppression mechanism, and is associated with a better prognosis." (PMID 32408477, 2020). "Similar to the discovery cohort, patients were scored for general tumor cell‐, perivascular‐, and endothelial NRP1 expression." (PMID 31880322, 2020). "Among them, ADARB1 had a lower expression in tumor tissues (P<0.05), and ETF1 and NRP1 were highly expressed in tumor tissues (P<0.05)." (PMID 32469390, 2020). "The delay in tumor growth upon Nb1-mediated blockade of NRP-1 only became apparent in later stages of tumor growth (week 3) when the TME is established." (PMID 33266104, 2020). "Among the 314 patients included in the TMA, 297 yielded informative staining; 224 (75%) were positive for tumor cell‐NRP1, 208 (70%) for perivascular NRP1, and 93 (31%) for endothelial cell‐NRP1." (PMID 31880322, 2020). "In tumours, NRP1 promotes integrin α5β1 fibronectin fibril assembly activity and desmoplasia by favouring the interaction between the non-receptor tyrosine kinase ABL1 and the scaffolding protein GIPC." (PMID 32911833, 2020). "In summary, patients with high NRP1 expression in tumor cells and in particular in perivascular tumor cells, showed a preferential presence of trans complexes." (PMID 31880322, 2020). "NRP1 has been reported to modulate integrin signalling and extracellular matrix remodelling in ECs and tumours." (PMID 32911833, 2020). "The interaction between iRGD and NRP-1 overexpressed in endothelium cells is effectively utilized to penetrate tumor cells in targeted drug delivery systems." (PMID 32847045, 2020). "Neuropilin-1 (NRP-1) is a protein implicated in angiogenesis and therefore also plays a role in the vascularisation of tumours." (PMID 32781656, 2020). "General tumor cell NRP1 expression was similarly analyzed with respect to clinicopathological characteristics and outcome in both RCC cohorts." (PMID 31880322, 2020). "The homing sequence directs the peptide to the tumor vascular endothelium, while the tissue penetration motif, once activated by a protease, binds to a different receptor (neuropilin-1), which mediates extravasation and tissue penetration." (PMID 32854363, 2020). "Compared with RGD, the tumor targeting ability of iRGD is more intensified because iRGD can specifically bind to integrins and neuropilin-1 (NRP-1) receptors that are overexpressed on various tumors." (PMID 32847045, 2020). "NRP1 is a membrane receptor known to promote tumor growth and drug resistance in several cancers, including OC." (PMID 31898520, 2020). "CSC-secreted VEGF plays other critical roles in the tumor niche since it enhances CSCs proliferation by stimulating neuropilin-1, a co-receptor of VEGFR2, and thus promotes tumor progression and relapse." (PMID 33059744, 2020). "We found that VEGFR1/2 and NRP1 expression significantly decreased in the tumours that overexpressed miR-590." (PMID 32303680, 2020). "In the BxPC-3 xenograft model here, the VEGFA-and-NRP1 dual-targeting bispecific antibody (IDB0076) significantly retarded the tumor growth and tumor blood vessel formation as compared with the VEGFA-blocking monospecific antibody bevacizumab." (PMID 32560565, 2020). "NRP1 can participate in tumor development and promote tumor metastasis by eliciting a range of intracellular signaling cascades." (PMID 33014187, 2020).
tumor (continued). "Together, these data identified NRP1 expression in perivascular tumor cells as a novel independent marker for RCC patient prognosis." (PMID 31880322, 2020). "The co-administration of the iRGD peptide with gemcitabine resulted in effective drug accumulation and tumor reduction in patient-derived PDAC xenografts with NRP-1 overexpression." (PMID 32847045, 2020). "As HGF/cMET inhibits apoptosis and promotes immune tolerance by interacting with the programmed death ligand 1 (PD-L1), the stimulation of this signaling pathway by NRP1 promotes tumor growth by inhibiting the antitumor immunity." (PMID 32766254, 2020). "Knockdown of NRP1 inhibited GC cell growth, migration and invasion in vivo, and suppressed xenograft tumor development in vivo." (PMID 32508529, 2020). "Although many studies have focused on NRP‐1 function in tumour angiogenesis, only a few have examined the expression of NRP‐1 on tumours cells." (PMID 32951327, 2020). "NRP1 has been suggested as a therapeutic target for cancers owing to its tumor promoting roles in various cancers." (PMID 32408477, 2020). "Neuropilin 1 is over-expressed in breast, prostate, pancreatic, colon, and kidney cancers, and exerts important roles in tumor progression, angiogenesis and anti-cancer immunity." (PMID 32184727, 2020). "NRP1 can promote tumor angiogenesis, cell proliferation, and cell migration, through a variety of mechanisms that play a vital role in the progression of cancer." (PMID 32472711, 2020). "Overexpression of soluble neuropilin-1 in cancer cells led to disturbed tumor vascularization and cancer cell apoptosis in xenografts." (PMID 32984308, 2020). "PL3-coated nanoparticles were found to accumulate in TNC-C and NRP-1-positive areas in clinical tumor samples, suggesting a translational relevance." (PMID 32242067, 2020). "The elevated expression in tumor, endothelial, and immune cells, makes NRP1 and 2 new relevant oncology targets to improve the treatment of cancers." (PMID 32766254, 2020). "Treg-restricted NRP1 deletion results in profound tumour resistance due to Tregs functional fragility." (PMID 32680511, 2020). "Destabilization of Treg cells by a deficiency of critical Treg-associated factors such as Nrp-1, SOCS1, EZH2, Eos or CARMA1 protects hosts from syngeneic tumor growth." (PMID 33024109, 2020). "In conclusion, NRP1 expression in the tumor cell compartment correlated with improved survival in two independent RCC cohorts, which was further supported by results from the KIRC ccRCC dataset." (PMID 31880322, 2020). "Neuropilin-1 is a protein found on most of the tumor-infiltrating Tregs, important for their suppressive function." (PMID 33005420, 2020). "Neuropilin1 (NRP1) acts as a co-receptor of various growth factors and plays a major role in tumor progression." (PMID 32408477, 2020). "Altered expression of NRP1 promotes tumor proliferation, angiogenesis, and metastasis by triggering vascular endothelial growth factor (VEGF) and other pathways." (PMID 33014187, 2020). "We observed that tumor growth was significantly delayed and survival prolonged when the anti-NRP-1 Nbs were produced in vivo." (PMID 33266104, 2020). "Formation of VEGFR2/NRP1 complexes in trans requires expression of VEGFR2 on endothelial cells and NRP1 by perivascular tumor cells." (PMID 31880322, 2020). "Knockdown of NRP1 markedly slowed tumor growth, with a much lower tumor weight compared with control group." (PMID 32508529, 2020). "This study provided a reference for exploring NRP1 gene further for molecular mechanisms of tumor invasion and metastasis, and suggests an important candidate target and new direction for the treatment of PACA." (PMID 32472711, 2020). "Rescue experiments validated that overexpression NRP1 partially abrogated the tumor suppressive function of miR-19b-3p." (PMID 32508529, 2020). "SGC-7901 cells stably knockdown NRP1 or control cells were subcutaneously inoculated into nude mice to establish the xenograft tumor." (PMID 32508529, 2020).
tumor (continued). "Expression of NRP1 in perivascular tumor cells was explored as a marker for RCC survival in the two RCC cohorts." (PMID 31880322, 2020). "In this study, we found a clear link between NRP‐1 expression and tumour differentiation, TNM staging and the CAFs activation marker α‐SMA." (PMID 32951327, 2020). "In the hypoxic core, NRP-1 expression on TAMs is transcriptionally repressed, as such trapping these cells in those tumor regions where they suppress the activity of NRP-1+ CD8+ T cells and stimulate Treg activity." (PMID 33266104, 2020). "MiR-19b-3p exerted its tumor suppressor function via negatively regulating NRP1 and EMT/focal adhesion process." (PMID 32508529, 2020). "Especially in various types of tumor, NRP1 has a critical role in cell migration, invasion and angiogenesis, promoting tumor progression." (PMID 32408477, 2020). "For vascular-targeted photodynamic therapy (VDT), newly synthesized AGuIX type nanoplatform using photosensitizer and KDKPPR peptide moiety targeting neuropilin-1 (NRP-1), which is highly expressed in the tumor vasculature, were developed (AGuIX@PS@KDKPPR)." (PMID 32883290, 2020). "There was a significant association between the presence of trans complexes and NRP1 expression in perivascular tumor cells (p‐value = 0.004), and between trans complexes and general NRP1 expression in tumor cells (p‐value = 0.036)." (PMID 31880322, 2020). "A novel iRGD peptide that exploits the tumor microenvironment can activate integrin-dependent binding to tumor vasculatures and neuropilin-1 (NRP-1)-dependent transport to tumor tissues." (PMID 32847045, 2020). "NRP1 enhances Treg cells for tumor infiltration and promotes macrophage differentiation, as preparation for the activation of immune evasion responses." (PMID 32408477, 2020). "The cytokine array cluster analysis revealed IL‐8 secreted by CAFs facilitated the up‐regulation of NRP‐1 in tumour cells." (PMID 32951327, 2020). "The micelle was composed of a NRP-1 tumor-targeting peptide (AKRGARSTA), a histidine-rich domain, and cholesterol." (PMID 32823960, 2020). "We have previously reported that NRP1 can orchestrate such mechanisms in different tumor cell types." (PMID 32784465, 2020). "NRP-1 is a cell surface glycoprotein that appears to be crucial for tumor angiogenesis, growth, and metastasis." (PMID 32560392, 2020). "Multivariable analysis was performed on both cohorts including perivascular or general tumor cell expression of NRP1 together with sex, age, histology, MSKCC‐score, Fuhrman grade, T stage, and M stage." (PMID 31880322, 2020). "In cholangiocarcinoma, NRP1 contribution to the growth and metastasis of tumor cells is regulated by miR-320." (PMID 31898520, 2020). "It is notable that patients who had tumors that were positive for perivascular tumor cell expression of NRP1 also exhibited less‐vascularized tumors and improved overall survival." (PMID 31880322, 2020). "Both Nrp1-KD and PlxnA1-KD demonstrated a slower rate of growth than NT-BTSCs, as determined by changes in tumor diameter, though only Nrp1-KD reached statistical significance." (PMID 33302912, 2020). "NDGA impacts metastasis of tumor cells through LOX inhibition but also due to down-regulation of neuropilin 1, a single-pass transmembrane protein that functions as a “signaling platform” on the cell surface." (PMID 32184727, 2020). "Neuropilin 1 expression on tumor cells enhances cell viability, proliferation, migration, metastasis and favors cancer cell stemness." (PMID 32766254, 2020). "KLA-iRGD inhibits tumor growth via activation of the receptor neuropilin-1 and subsequent internalization activity." (PMID 31346334, 2019). "NRP1-mediated endocytosis (micropinocytosis and a related, yet different process) allows tumor cells as well as other cells to take up nutrients." (PMID 30717262, 2019).
tumor (continued). "Anti-Nrp-1 plus anti-PD-1 combination immunotherapy would allow optimisation of tumour infiltration by CD8+ T cells and CTL reactivity toward target cells thereby improving immune protection and responses to immune checkpoint blockade." (PMID 31350404, 2019). "Results showed a much larger CD8+ T-cell infiltration in tumours obtained from mice treated with the anti-Nrp-1 i.p. plus anti-PD-1 combination than from mice treated with each mAb alone or the isotype control." (PMID 31350404, 2019). "Binding of VEGF-A to NRP1 favors growth and metastasis of solid tumors, whereas, binding of SEMA3A is generally associated with less migration and invasion of tumor cells and thus better prognosis." (PMID 30717262, 2019). "Cltx-NRP1 binding enhanced tumor uptake of ER-472 active metabolite that was blocked by anti-NRP1 antibody treatment or NRP1 knockdown and resulted in diminished ER-472 antitumor activity." (PMID 31208428, 2019). "On the other hand, binding of SEMA3 to NRP1 also has adverse side effects, such as attraction of tumor-promoting macrophages and increase in vascular permeability." (PMID 30717262, 2019). "At the protein level, we also found an expression of Nrp-1 on some epithelial tumour cells from freshly dissociated human NSCLC and on all the tested lung tumour cell lines." (PMID 31350404, 2019). "The analysis of data indicated that the levels of plasma NRP-1 were increased significantly (p = 0.026) in patients who remained with a large tumor size (n = 9, ypT1&2) and partially responded to the treatment (p = 0.018) (n = 13, pPR)." (PMID 31106153, 2019). "These different observations - pro-tumorigenic effects of NRP1 on the one side and tumor suppressing effects of NRP1 on the other - were attributed to the status of activating K-Ras mutations in pancreatic cancer." (PMID 31664117, 2019). "VM as well as tumor cell invasiveness correlates with increased NRP1 expression due to upregulation of VEGF-A, secretion of matrix metalloproteinase (MMP)-2 and -9, and activation of αvβ5 integrin." (PMID 30717262, 2019). "Following the prevailing view that NRP1 is a tumor promoter, several studies have been performed to test NRP1 as a therapeutic target." (PMID 30717262, 2019). "In general, NRP1 expression has been associated with cancer progression in multiple types of solid tumors, and diverse NRP1-targeting agents have been demonstrated to have tumor suppressing activity in mouse preclinical models." (PMID 31143707, 2019). "Engagement of Nrp1 promoted Treg quiescence and limited differentiation, resulting in enhanced Treg stability in the tumor." (PMID 31118303, 2019). "Then, apoptosis was rapidly triggered by m(KLA)-iRGD through the mitochondrial-induced apoptotic pathway and the death receptor pathway in NRP1+/αvβ3/Cathepsin B+ tumor cells." (PMID 31346334, 2019). "We checked in this model the effect of i.p. administration of anti-Nrp-1 on tumour growth and weight, and found that it was much more efficient than the i.t. route." (PMID 31350404, 2019). "Since tumor angiogenesis is dependent on tip cell formation, which is essentially modulated by the interaction of Notch and NRP1-mediated Smad2/3 signaling, inhibition of NRP1 is an attractive target for restraining tumor angiogenesis." (PMID 30717262, 2019). "The ATWLPPR heptapeptide showed high binding specificity to NRP-1 but a relatively low tumor accumulation." (PMID 31394799, 2019). "As in normal arteries, NRP1 occurs on the basolateral side of TEC of intrinsically leaky tumor vessels." (PMID 30717262, 2019). "The tumor growth rate and tumor volume of each group were positively correlated with NRP1 expression." (PMID 31417646, 2019). "It has also been reported that inhibition of Sema-3C binding to Nrp-1 with small molecules attenuates tumour growth in prostate cancer." (PMID 31350404, 2019).
tumor (continued). "Results showed much larger CD8+ T-cell infiltrates in tumours obtained from mice treated with the anti-Nrp-1 plus anti-PD-1 combination than from mice treated with each mAb alone or the isotype control." (PMID 31350404, 2019). "Results showed that intra-tumoural (i.t.)administration of anti-Nrp-1 mAb, or intra-peritoneal (i.p.)injection of anti-PD-1 mAb, inhibited tumour growth as compared with control treatment." (PMID 31350404, 2019). "In our study, we used tumor-bearing model in vivo for confirming the role of NRP1 in tumor microenvironment around the cancer cells." (PMID 31417646, 2019). "Tumor-produced VEGF-A attracts Nrp1-expressing Tregs and this interaction mediates Tregs infiltration into the tumor." (PMID 32039024, 2019). "Based on these findings we propose that NRP1 tumor level be assessed prior to future clinical application of Cltx-based therapeutic or diagnostic agents for cancer therapy." (PMID 31208428, 2019). "In this regard, the selection of a tumor PDX pair with differential NRP-1 expression on the tumor vasculature demonstrated differences in carrier uptake and irinotecan delivery during iRGD-mediated transcytosis activation." (PMID 31754378, 2019). "The expression of NRP-1 in TNBC tumor sections was significantly downregulated in response to electroacupuncture treatment given daily for 3 weeks." (PMID 31839752, 2019). "More metabolite in the presence of NRP1 indicates increased tumor uptake via binding of Cltx-derived peptides to NRP1 and is a compelling and plausible mechanism by which the observed amplified antitumor response was achieved." (PMID 31208428, 2019). "In contrast, depletion of RAB7 by RNA interference blocks transfer of NRP-1 to lysosomes, causing increased NRP-1 expression, increased angiogenesis and increased tumor growth." (PMID 31374919, 2019). "Kinetic studies revealed that the percentage of Nrp-1+ CD8+ TIL increased during tumour growth, with similar induction of PD-1, LAG-3 and Tim-3 and, to a lesser extent, CTLA-4." (PMID 31350404, 2019). "A new sterically stabilized liposome (SSL) with DOX-loaded and iRGD-modified (iRGD-SSL-DOX) was applied to B16-F10 cells in vitro and to tumor-bearing mice in vivo because αv integrin receptor and NRP-1 were also overexpressed in B16-F10 cells." (PMID 31346334, 2019). "The involvement of Nrp1 in the growth of new blood vessels in tumor vasculature promotes tumor progression, and its blockade can restrict tumor growth." (PMID 31118303, 2019). "CGNKRTR (tLyp-1) is one of the most promising homing peptides, which penetrates tumor cells through a neuropilin-1 (NRP-1) mediated endocytosis via the C-end Rule (CendR) internalization pathway." (PMID 31546717, 2019). "In consistent with the in vitro results, immunoblotting analysis of tumor homogenates showed that miR-141 mimics induced upregulation of p27 and E-cadherin, and downregulation of NRP-1, CDK2, cyclin E, Snail and N-cadherin." (PMID 31572065, 2019). "In particular, NRP1-deficient Treg cells were found to release IFN-γ, which in turns suppresses Treg activity, unleashing an anti-tumor immune response." (PMID 31027288, 2019). "In this way, NRP1 is involved in nutrient uptake by tumor cells, and its surface expression inversely correlates with nutrient supply." (PMID 30717262, 2019). "The NSCLC tumour sample 8 was found to display a high increase in Nrp-1 mRNA expression, and NSCLC samples 1, 2 and 4 were found to display about a two fold expression increase compared with autologous healthy lungs." (PMID 31350404, 2019). "We therefore assume that Nrp-1 can be used as a marker for identifying this important CD8+ tumour-reactive TIL population." (PMID 31350404, 2019). "Interaction of Nrp-1 with its ligand semaphorin-3A inhibits migration and tumour-specific lytic function of cytotoxic T lymphocytes." (PMID 31350404, 2019). "Such downregulation of NRP1 in oncogenically KRAS-transformed cells promotes tumor growth by reducing SMAD2 phosphorylation." (PMID 30717262, 2019).